STAT3 (signal transducer and activator of transcription 3)
Diseases named in the same sentence as STAT3 in open-access papers (continued):
Sharing a sentence is not in itself a finding about the gene and the disease.
tumor (continued). "Several lines of evidence indicate that niclosamide inhibits tumor cell growth by interrupting multiple pathways (Wnt, Notch, STAT3, NF-κB, and mTORc1) and the generation of reactive oxygen species in several cancer cells." (PMID 26848771, 2016). "Meanwhile, VEGF-induced activation of STAT3 also plays a critical role in angiogenesis, and this signaling pathway is a potential target for antiangiogenic tumor therapy in endothelial cells." (PMID 27203384, 2016). "STAT3-driven inhibitory effects on the production of chemokines and inflammatory mediators by tumor cells, inhibition of DC maturation, and the production of IL-12 can block NK activity within the tumor microenvironment." (PMID 27148255, 2016). "There, induced STAT3 activation is considered to impair tumor immune surveillance and allows the tumor to escape immune control." (PMID 28149296, 2016). "Blocking STAT3 activation in murine tumor models alters the cytokine profile of tumor cells and tumor-infiltrating hematopoietic cells, and re-establishes proinflammatory, tumoricidal activity." (PMID 27148255, 2016). "STAT3 is constitutively activated in many different cancer types and plays a pivotal role in tumor growth and driving metastasis, including BMs." (PMID 26959886, 2016). "Collectively, our results suggest that BP-E and BP-E-F1 can effectively suppress the differentiation and function of gMDSCs via inhibition of tumor-derived G-CSF-induced activation of STAT3." (PMID 27857157, 2016). "Total STAT3 tumour cell expression correlated strongly with ph-STAT3 tumour cell expression (P<0.001)." (PMID 27769057, 2016). "Consistent with the in vitro results, in vivo xenograft experiments showed the TKI-resistant tumor-selective growth inhibition and suppression of Src-Stat3-dependent signaling in the GA-treated tumors isolated from the xenograft model." (PMID 27419630, 2016). "High ph-STAT3 was significantly associated with improved CSS in luminal A (n=174) (P=0.005) and B (n=92) tumours (P=0.017)." (PMID 27769057, 2016). "We also observed decreased STAT3 activation and cyclin D1 expression in tumor biopsies from HepG2-WT-HCMV-injected mice as compared with controls." (PMID 27626063, 2016). "STAT3 activation in tumor cells can regulate their sensitivity to NK-mediated killing by altering the expression of NK-activating ligands on the cell surface." (PMID 27148255, 2016). "NF-κB and STAT3 enhance resistance to apoptosis-based tumor surveillance of pre-neoplastic and malignant cells." (PMID 27191495, 2016). "Total and ph-STAT1 and STAT3 expression in tumour cells were quantified using the weighted histoscore, taking the staining intensity and percentage into account." (PMID 27769057, 2016). "In support of this possibility, previous studies have shown that integrin α6β4 cooperates with HER2 to drive STAT3 activation during tumour progression." (PMID 27035095, 2016). "STAT3 has been reported to play an important role in maintaining cancer stem cells both in vitro and in vivo, implicating an integral involvement of STAT3 in tumor initiation, progression, and maintenance." (PMID 27190500, 2016). "B16F10 cells express high levels of the DNAM-1 ligand CD155 and thus enhanced lysis of B16F10 tumor cells by STAT3−/− NK cells was abrogated by treatment with a DNAM-1 blocking antibody." (PMID 27148255, 2016). "Signal transducer and activator of transcription proteins 3 (STAT3) is well demonstrated to play a crucial role in tumor development and cancer-related inflammation." (PMID 26959884, 2016). "For example, miR-124 can inhibit tumor by directly targeting STAT3, a key component mediating immunosuppression in the tumor microenvironment." (PMID 27757114, 2016). "It is plausible that STAT1 and STAT3 have prognostic value in different tumour types, different molecular subtypes or in different aspects of the tumour microenvironment." (PMID 27769057, 2016).
tumor (continued). "STAT3 is constitutively activated in many cancers and plays a pivotal role in tumor growth and metastasis." (PMID 27274723, 2016). "Several studies have shown that STAT3 activation can disrupt interactions between immunocompetent cells in the tumor microenvironment and induce an immunosuppressive milieu." (PMID 27148255, 2016). "STAT3 was shown to be a direct transcriptional activator of the IL-12p19 gene, and IL-23 in the tumor microenvironment inhibited IL-12 production by tumor-associated DCs." (PMID 27148255, 2016). "Conversely, increased NK-mediated tumor cell killing conferred by STAT3 decoy oligonucleotide was reversed by the addition of exogenous TGF-β." (PMID 27148255, 2016). "Mechanistically, resveratrol inhibited cancer metastasis through upregulation of microRNA-34a activity, which act as an important tumor suppressor and is downregulated by STAT-3." (PMID 27834913, 2016). "Results from this study show that LIF induces the expression of miR-21 through the STAT3 signaling in human tumor cells." (PMID 26716902, 2016). "This shows the ability of icariside II to overcome the survival signals of tumor cells because STAT3 is one of the STAT proteins that is constitutively active in cancer cells where it promotes the expression of antiapoptotic proteins." (PMID 27445824, 2016). "We found that compared to the normal tissues the HNSCC patients' tumor tissues displayed higher expression of STAT3 or Src." (PMID 27682875, 2016). "STAT3 was involved in many tumor development and progression, and also played an important role in cancer stem cell." (PMID 27494878, 2016). "Given the presence of STAT3 in the retina and its involvement in tumor angiogenesis, we examined its role in retinal neovascularization." (PMID 27210483, 2016). "Our results suggest that STAT3, a central checkpoint at the intersection between inflammation and tumor development, is involved in miR-373 signaling in cancerous IEC." (PMID 27271572, 2016). "PBISe promoted apoptosis by inhibiting PI3K, MAPK, and STAT3 signaling with significant reduction in the tumor sizes (p < 0.007)." (PMID 27023566, 2016). "Signal transducer and activator of transcription 3 (STAT3) plays important roles in tumor cell proliferation, survival, invasion and immunosuppression." (PMID 26506239, 2016). "Activation of the JAK/STAT3 pathway protects tumor cells from Fas-mediated apoptosis by upregulating the anti-apoptotic proteins Mcl-1, Bcl-XL and c-Myc." (PMID 27474171, 2016). "In contrast, depletion of STAT3 in HT-29 and LS174T (high STAT1+low STAT3) resulted in growth reduction, as assessed by tumor growth curves and tumor weight at end point analysis." (PMID 27191495, 2016). "HCCR and p-STAT3 expression levels in tumours developed from HCCR-shRNA1-transfected cells were significantly lower than in those from control-shRNA-transfected cells (P < 0.05)." (PMID 27052330, 2016). "The mechanisms how IL-22 confers stemness in tumor cells compared with other pro-tumorigenic cytokines also signaling through STAT3, such as IL-6 and IL-11, warrant further investigation." (PMID 27148488, 2016). "The sporadic distribution of STAT3-inactivated apoptotic foci in tumor tissues and the eventual death of resveratrol-treated tumor-bearing animals suggest the necessity to combine LP resveratrol with surgical resection for more promising therapeutic outcomes." (PMID 27716625, 2016). "STAT3 indirectly inhibits E-cadherin, which is involved in EMT, given that a loss of E-cadherin triggers tumor metastasis and EMT." (PMID 26824417, 2016). "Signal transducer and activator of transcription 3 (STAT3) or enhancer of zeste homologue 2 (EZH2) is the potential molecular biomarker for tumor progression and mainly serve as the poor predictor of outcome." (PMID 27938379, 2016). "As anticipated, before CPA-7 treatment, the level of p-STAT3 was high in the infiltrating area between the tumor tissues and the adjacent muscle tissues." (PMID 27435207, 2016).
tumor (continued). "We observed that co-injection of tumor cells with MSCs dramatically increased the p-STAT3 levels in the tumor." (PMID 27340780, 2016). "According to previous studies, STAT3 has been shown to promote tumor progression, whereas STAT1 tend to suppress it." (PMID 27486982, 2016). "Growing evidence suggests that JAK2/STAT3 signaling can be activated by IL-6 and this activation is required for tumor initiation and progression." (PMID 27367272, 2016). "Aberrant activation of STATs, especially of STAT3, contributes to tumour progression at several levels." (PMID 27406745, 2016). "Activated Stat3, subsequently, regulated tumor growth, enabling cancer cells to survive under pressure of targeted therapies." (PMID 27419630, 2016). "Further, CCK-BR, STAT3, p-STAT3, Akt and p-Akt expression level were detected in the tumor sections removed from the mice." (PMID 27518872, 2016). "Oncogenic activation of STAT3 and NF-κB induces cytokine production by tumor cells that can regulate immunosuppressive and tumor-promoting functions of tumor infiltrating immune cells via trans-activation of these same transcription factors." (PMID 27784305, 2016). "In current study, we confirmed that Sal caused the inhibition of proliferation, and induced substantial apoptosis in tumor cells by prohibiting constitutive STAT3 activation in SGC-7901 cells and thereby its DNA binding ability." (PMID 27058891, 2016). "The role of STAT3 in anticancer immunity and therapy becomes even more complex in light of studies suggesting that STAT3 can promote NK-mediated tumor immunity." (PMID 27148255, 2016). "In conclusion, STAT1 and STAT3 tumour cell expression appears to be an important determinant of favourable outcome in patients with invasive ductal breast cancer." (PMID 27769057, 2016). "Similar to NF-kB, STAT3 is constitutively activated in both tumor and immune cells increasing tumor cell proliferation, survival and invasion and is activated by NFkB-induced genes such as Interleukin 6 (IL6)." (PMID 27349385, 2016). "Taken together, our results suggest that miR-148a serves as a tumor suppressor in human gastric carcinogenesis by targeting CCK-BR via inactivating STAT3 and Akt." (PMID 27518872, 2016). "STAT3 signaling is required for immunosuppressive and tumor-promoting functions of MDSCs, as well as for Treg cell expansion." (PMID 26621531, 2016). "Engagement of IL-6 with its receptor leads to activation of STAT3, which promotes the proliferation of cancer cells and tumor progression." (PMID 27148488, 2016). "EBI3 blocking peptide promoted antitumor cytotoxic T lymphocyte (CTL) response by inducing Granzyme B, IFN-γ production, and p-STAT3 expression and inhibited CRC cell proliferation and tumor growth to associate with suppressing gp130 and p-STAT3 expression." (PMID 27247488, 2016). "For example, NPM-ALK has been shown to induce promoter DNA methylation of tumor suppressors via its downstream target STAT3, which is also a highly relevant TF in ALK− ALCL." (PMID 27705804, 2016). "STAT3 Y705 phosphorylation was consistently higher in Δp/np than in F/F tumours and correlated with the expression of the GP130 subunit of the IL6 receptor, which has been implicated in gastrointestinal tumourigenesis." (PMID 28000790, 2016). "To determine the association of the SHP-1/p-STAT3/VEGF-A cascade and tumor metastatic ability, we analyzed the protein expression of SHP-1, p-STAT3, and VEGF-A in several TNBC cell lines." (PMID 27364975, 2016). "Mechanistically, we uncover an innovative mechanism of the regulation of Notch2 via the JAK/STAT3 signaling pathway and subsequently-induced tumor malignancy in response to the radiation." (PMID 27462787, 2016). "We will discuss the interaction of STAT3 and hypoxia-inducible factor (HIF) as the hypoxic environment of the tumor is considered to be the main cause of clinical radiotherapy resistance." (PMID 27029037, 2016).
tumor (continued). "Activated STAT3 promotes tumor cell survival, proliferation, angiogenesis/metastasis, and immune escape." (PMID 26910842, 2016). "Tumor cells become addicted to STAT3 signaling via the constitutive expression of STAT3-activating growth factors and cytokines or constitutively active mutations of RTKs or cytoplasmic kinases." (PMID 27148255, 2016). "Using immunofluorescence to further characterize the cellular populations expressing mCLCA5 and nuclear Stat3 (as a surrogate read-out of Stat3 activity), we identified at least two different cell populations at the edge of the tumour." (PMID 27711075, 2016). "Critical involvement of NK cells in tumor rejection was demonstrated by showing that STAT3 deletion impaired H22 growth in nude mice, which lack T cells but have functional NK cells." (PMID 27148255, 2016). "Disruption of STAT3 signaling in the tumor microenvironment with concurrent TLR9 stimulation has potential to elicit effective antitumor immune responses without toxicities associated with pharmacologic agents." (PMID 27458169, 2016). "Reciprocal regulation of c-Src and Stat3 activation has been observed in non-small cell lung cancer cell lines (NSCLC) or tumor xenografts treated with anti-c-Src modalities and in NSCLC human patients." (PMID 26918609, 2016). "STAT-3 is a transcription factor that orchestrates an important part of the tumor immunosuppressive microenvironment in different ways." (PMID 27783034, 2016). "STAT3 promotes cancer proliferation and/or survival directly by regulating target genes of tumour cells such as survivin, cyclin D1 and Bcl-xL." (PMID 26909593, 2016). "In this regard, direct inhibition of STAT3 has been shown to reduce tumor growth and prolong survival in both animal models and human studies." (PMID 26686340, 2016). "In xenograft models, enhanced AF1q expression activated STAT3 and promoted tumor growth and metastasis in immunodeficient NSG mice." (PMID 27259262, 2016). "In contrast to STAT3 activation in normal cells, constitutive activation of STAT3 stimulates tumor cell proliferation and migration, mediates immune evasion, promotes angiogenesis, and confers resistance to apoptosis induced by conventional therapies." (PMID 26883202, 2016). "Particularly, STAT3 expression in the tumor microenvironment can modulate IL-12 and IL-23 secretion by immune cells such as dendritic cells (DCs) and macrophages." (PMID 26745884, 2016). "Recent studies in GBM and other tumours, however, have suggested an alternative role for STAT3 in tumour suppression." (PMID 27083054, 2016). "Increased activity of STAT3 correlates with various types of human tumors, while its repression can inhibit tumor progression." (PMID 27695477, 2016). "In respect of PC, STAT3 was suggested to be frequently over-expressed in vivo and vitro and play a pivotal role in the carcinogenesis of PC, while its anti-tumor effect in PC is scarcely reported so far." (PMID 27577070, 2016). "Perhaps the most important (and complex) role for STAT3 in NK function is as a regulator of cell–cell communication within the tumor microenvironment." (PMID 27148255, 2016). "In comparison to normal brain tissue and cells, particularly astrocytes, GBM expresses high levels of STAT3 and inhibition of this molecule results in the induction of apoptosis and cessation of tumor proliferation." (PMID 27148537, 2016). "JAK2/ STAT3 signaling regulates several important pathways in tumorigenesis including cell cycle progression, apoptosis, tumor invasion, and metastasis." (PMID 26755649, 2016). "The β1 activation subsequently results in phosphorylation of non-receptor tyrosine kinase FAK/Src and Syk, which in turn activates STAT3 and Akt, leading to the promotion of tumor cell survival." (PMID 26848618, 2016).
tumor (continued). "Results showed that 4-MD effectively suppressed the expression of proliferation marker (Ki-67 and Proliferating cell nuclear antigen (PCNA), ant-apoptotic molecule (Survivin), and therapeutic target molecule (p-STAT3) in tumor tissues." (PMID 26755649, 2016). "Cytokines produced by tumor cells activate STAT3 in NK cells, DCs, T cells, and macrophages that profoundly affect each population intrinsically and via critical crosstalk mechanisms that shut down both innate and adaptive immunity." (PMID 27148255, 2016). "Persistent phosphorylation of signal transducers and activators of transcription 3 (STAT3) is frequently observed in tumor cells." (PMID 25788267, 2015). "Stat-3 is a point of convergence for many signaling pathways involved in cell proliferation, tumor growth, and angiogenesis, and its expression correlates with the expression of VEGF in human cancer cell lines." (PMID 25608686, 2015). "The previous study show that nuclear PKM2 enhances the proliferation of tumor cells by phosphorylating STAT3 at Y70511." (PMID 26542452, 2015). "Signal transducer and activator of transcription 3 (STAT3) plays a critical role in tumor development by regulating signaling pathways involved in cell proliferation, survival, metastasis and angiogenesis." (PMID 26272737, 2015). "Compelling evidence has established that constitutive and aberrant activation of STAT3 occur in malignant gliomas and play a pivotal role in malignant transformation, tumor cell survival and angiogenesis." (PMID 25789853, 2015). "The IL-6/JAK/STAT3 pathway is appealing, as it links tumor-derived signaling and tumor microenvironment-initiated signaling." (PMID 26593949, 2015). "Both NF-κB and STAT3 mediated signals derived from tumor cells or infiltrating immune cells such as IL-1β, TNF-α, ROS or TLRs play a key role in the inflammatory activation of stromal fibroblasts associated to pathologies such as RA and cancer." (PMID 26501341, 2015). "STAT3 can directly bind to the promoter of VEGF further to upregulate the expression of VEGF in tumor cells." (PMID 26788112, 2015). "STAT3 also controls additional genes driving proliferation, suppression of apoptosis and aggressive tumor behavior." (PMID 26158901, 2015). "Intriguingly, in vivo blocking of IL-6/STAT3 signalling by the JAK1/2 inhibitor ruxolitinib in human LNCaP xenografts showed significantly enhanced tumour size and weight." (PMID 26198641, 2015). "miR-21 which is abundantly expressed in various tumor cells, is a direct STAT3 target in Sezary cells." (PMID 26464811, 2015). "In this study, we demonstrated that the miR-197/CKS1B/STAT3-mediated signaling drives tumor PD-L1 expression, allowing it to function as a biomarker for this cascade in NSCLC." (PMID 25597412, 2015). "Recently, STAT3 signal blockade has been shown to inhibit the prostate tumor-propagating and bulk tumor cell populations in patient-derived PCa xenograft models, as well as block tumor angiogenesis." (PMID 25595909, 2015). "The respective results suggested that significant relationship between overexpression of p-STAT3 in tumor samples was detected both in the digestive tract cancer and digestive gland cancer subgroups." (PMID 26024373, 2015). "We suggest that off-target effects of angiogenesis inhibitors targeting STAT3 are worth considering as a therapeutic option for patients who develop cachexia, independently of their anti-tumor activity." (PMID 25460504, 2015). "Recent studies have revealed persistent STAT3 activation in myeloid and T cells at primary tumor sites contribute to tumor-related immunosuppression, angiogenesis, growth and metastasis." (PMID 28031890, 2015). "Initial evidence of the role of STAT proteins in tumor biology came from the discovery that activated STAT3 was required for cellular transformation by the viral oncogene, v-src." (PMID 26272737, 2015).